ENSG00000232721 (novel transcript)
Gene: Long non-coding RNA gene on chromosome 1 (143,729,470 to 143,739,506, forward strand). Ensembl gene ENSG00000232721.
Gene Ontology:
Molecular function: pre-mRNA 5'-splice site binding; triplet codon-amino acid adaptor activity
Biological process: mRNA 5'-splice site recognition; translation
Cellular component: U1 snRNP